ASIC3 (acid sensing ion channel subunit 3)
Diseases named in the same sentence as ASIC3 in open-access papers (continued):
Sharing a sentence is not in itself a finding about the gene and the disease.
Anxiety (6 papers, 2009 to 2024). Intense feelings of nervousness, tension, or panic often arise in response to interpersonal stresses. "These genetic variants of ASIC3, rs2288645, rs2288646, and rs4148855 had been reported to be associated with human diseases, such as hypertension, pain, anxiety, and insulin resistance." (PMID 30804886, 2019). "Genetic variants of ASIC3, in terms of rs2288645, rs2288646, and rs4148855, had been reported to be associated with human diseases, such as hypertension, pain, anxiety, and insulin resistance." (PMID 30804886, 2019). "Here we undertook to investigate the properties of nmrASIC3 because evidence supports a role for ASIC3 in a wide variety of situations, including: pain (9, 23, –, 26), as well itch, mechanosensation, and anxiety." (PMID 29237731, 2018). "In contrast, Asic3−/− mice showed normal visual acuity, olfactory acuity, and anxiety levels & locomotion activity based on visual cliff, olfaction habituation tests, and open-field test respectively." (PMID 19652708, 2009). "Furthermore, ASIC3 is expressed within neuronal cells in the brain and adipocytes, and ASIC3 knockout mice show reduced anxiety levels and enhanced insulin sensitivity." (PMID 36830598, 2023). "Understanding the structure-function of ASIC3 is of particular interest because there is substantial evidence supporting involvement of ASIC3 in pain (9, 23, –, 28), as well itch, mechanosensation, and anxiety." (PMID 29237731, 2018). "To test this hypothesis, we first examined the effects of expressing ASIC3 in brain on tests of innate fear and anxiety, including predator odor-evoked freezing, CO2-evoked freezing and open-field behavior, all of which are impaired by ASIC1a disruption." (PMID 21324060, 2011).
fibromyalgia (6 papers, 2014 to 2024). A chronic disorder of unknown etiology characterized by pain, stiffness, and tenderness in the muscles of neck, shoulders, back, hips, arms, and legs. "ME/CFS patients with comorbid fibromyalgia also showed higher levels of mRNA in acid-sensing ion channel 3 (ASIC3) and P2X5." (PMID 37226227, 2023). "In a mouse model of fibromyalgia induced by repeated intramuscular acid injections, ASIC3 and TRPV1 play essential roles in acute pain induction, hyperalgesic priming, and the development of chronic pain." (PMID 30486810, 2018). "Similarly, ASIC3 was found to be the major molecular determinant in two other fibromyalgia pain models induced by intermittent cold stress or repeated and intermittent sound stress." (PMID 37417654, 2024). "Intriguingly, proprioceptors highly express the pro‐nociceptive ASIC3, which is a molecular determinant involved in the acid‐induced pain model and pain chronicity in two other mouse models of fibromyalgia induced by intermittent cold stress or repeated and intermittent sound stress." (PMID 37417654, 2024). "Thus, here we propose that the soreness phenotype of fibromyalgia is an imbalanced acid signaling between acid-induced nociception and acid-mediated anti-nociception, mainly due to impaired non-ASIC3, non-TRPV1 acid signaling." (PMID 30486810, 2018). "ASIC1b, ASIC3 and TRP channel subfamily V member 1 (TRPV1) were found to be the molecular determinants of acid‐induced fibromyalgia‐like pain in mice." (PMID 37417654, 2024). "Accumulating evidence has shown ASIC3 and TRPV1 as two major acid sensors in nociceptors that trigger acid-induced pain in mouse models of fibromyalgia." (PMID 30486810, 2018). "The involvement of ASIC3 channels in this pathology was proposed based on their potentiation by LPC, as excessive oxidative stress and LPC (the LPC16:0 species) levels were reported in patients with fibromyalgia." (PMID 36287977, 2022). "Thus, probing the molecular determinants that contribute to the non-ASIC3, non-TRPV1 acid signaling will be a key step to reveal the mystery of fibromyalgia, especially for individuals who have soreness phenotypes and are resistant to acupuncture analgesia." (PMID 30486810, 2018). "Although the molecular identity of the ASIC3‐, TRPV1‐independent acid sensors is unknown, a possible candidate is ASIC1a, because ASIC1a can mediate anti‐nociceptive signalling in muscle afferents in response to dextrose prolotherapy in the acid‐induced fibromyalgia model." (PMID 37417654, 2024).
glioblastoma (6 papers, 2017 to 2025). The most malignant astrocytic tumor (WHO grade IV). "Activation of ASIC3 with GMQ causes selective depolarization of glioblastoma CSCs, resulting in cell damage." (PMID 40806720, 2025). "In glioblastoma stem cells (GSCs), which are key contributors to therapy resistance in malignant glioma, functional ASIC1a and ASIC3 channels are expressed." (PMID 40806720, 2025). "We previously reported that primary glioblastoma stem cells (GSCs), which grow as multicellular tumour spheroids, express functional ASIC1a and ASIC3, whereas ASIC2a is downregulated in GSCs." (PMID 36522586, 2023). "A recent study from Dr. Grunder's group reported that glioblastoma stem cell (GSC) lines (R8 and R54) express functional ASIC1 and ASIC3, and their data suggest that expression of ASICs is associated with an improved survival in GSC lines." (PMID 34557113, 2021). "More recently, ASIC1a and ASIC3 have been found in glioblastoma cancer stem cell lines, whether or not they form heteromeric ASIC1a/3 channels is unclear." (PMID 32887365, 2020).
rheumatoid arthritis (6 papers, 2014 to 2022). A chronic, systemic autoimmune disorder characterized by inflammation in the synovial membranes and articular surfaces. "Acid-sensing ion channel 3 (ASIC3) is an important pain transducer predominantly expressed in muscle nociceptors and involved in pain-associated tissue acidosis, such as inflammatory pain, rheumatoid arthritis, post-operative pain, chest pain, postoperative pain, and so on11–13." (PMID 31431652, 2019). "Recently, in a mouse model of rheumatoid arthritis a link between bone erosion and pain was found in a state of subclinical inflammation that could be relieved by APETx2 and ASIC3 genetic invalidation." (PMID 36287977, 2022). "A previous work has also demonstrated an increased expression of ASIC3 on nerve afferents supplying joints in response to inflammatory stimulus and an anti-inflammatory action exerted by ASIC3 inhibitors in animal models of rheumatoid arthritis." (PMID 34690702, 2021). "Experiments were performed in cultured FLS from wild-type (WT) and ASIC3-/- mice, ASIC1-/- mice, and people with rheumatoid arthritis." (PMID 24923411, 2014). "Another similar example is observed in ipsilateral joints suffering from rheumatoid arthritis, in which three proton sensors contribute to inflammation and pain: TDAG8, transient receptor potential vanilloid subtype 1 (TRPV1), and acid-sensing ion channel 3 (ASIC3)." (PMID 35247105, 2022). "Regarding joint pain, ASIC3 was found to be expressed in more than 30% of DRG neurons innervating the knee joint in mice, and ASIC expression in DRG is increased in mice models of acute arthritis or rheumatoid arthritis." (PMID 36287977, 2022).
bone cancer (5 papers, 2021 to 2023). A primary or metastatic malignant neoplasm affecting the bone or articular cartilage. "The inhibition of ASIC3, which responds to the bone stroma-degrading proton H1 secreted by osteoclasts, attenuates pain-related behavior in bone cancer pain models." (PMID 37664239, 2023). "In the bone cancer pain induced model of Sprague Dawley rats, resveratrol administration significantly downregulated the expression of acid-sensing ion channels 3 (ASIC3) to alleviate the pain." (PMID 34681206, 2021). "Notably, we revealed that the underlying analgesic mechanisms of Metformin on bone cancer pain are in part via reducing the expression of TRPV1 and ASIC3." (PMID 34421611, 2021). "Therefore, the upregulation of ASIC3 may be a potential factor in the development of pain in bone cancer." (PMID 37664239, 2023). "However, whether ASIC3/TRPV1 is involved in the analgesic effect of Metformin on bone cancer pain remains unclear." (PMID 34421611, 2021). "ASIC3 is a pH sensor that responds to slight extracellular acidification, and was found obviously enhanced with TRPV1 in the DRG in rats of bone cancer models." (PMID 37250405, 2023).
myocardial ischemia (5 papers, 2005 to 2024). A disorder of cardiac function caused by insufficient blood flow to the muscle tissue of the heart. "Also, Asic3−/− mice show impaired triggering of pain associated with tissue acidosis under the conditions of surgery, cardiac ischemia, muscle and joint inflammation, and rheumatoid arthritis." (PMID 29793480, 2018). "Lastly, we wondered whether loss of ASIC3 had any effect on the myocardium under chemical stimulation such as cardiac ischemia." (PMID 24804235, 2014). "ASIC3 functions as a sensitive pH and lactate sensor during myocardial ischemia, and its activation can trigger harmful neuronal reflexes." (PMID 39712499, 2024). "ASIC3 generates sustained currents within the extracellular pH range of 7.3 to 6.7 during myocardial ischemia in rats." (PMID 39712499, 2024). "Accordingly, homomeric ASIC3 (in rats) and heteromeric ASIC2/ASIC3 (in mice) are the major chemo-sensing transducers in cardiac ischemia-sensing afferent neurons." (PMID 29793480, 2018). "Recent studies demonstrate that acid-sensing ion channel 3 (ASIC3) is a sensitive acid sensor for cardiac ischemia and prolonged mild acidification can open ASIC3 and evoke a sustained inward current that fires action potentials in cardiac sensory neurons." (PMID 24804235, 2014). "This is supported by studies showing that ASIC3 reproduces the functional features of cardiac ischemia-sensing neurons." (PMID 24804235, 2014). "Since those neurons are composed of major cardiac afferents, ASIC3 may help to transduce angina, the chest pain that accompanies cardiac ischemia." (PMID 24804235, 2014). "Furthermore, this extracellular acidification process could activate cardiac acid-sensing ion channel 3 (ASIC3) exclusively on sensory neurons, like in myocardial ischemia and as suggested in DOMS." (PMID 37999426, 2023). "Therefore, future studies involving Asic3−/− mice as a model for acid-evoked reflex loop during angina would provide valuable and informative clues to the therapeutic strategies for patients with cardiac ischemia." (PMID 24804235, 2014).
glioma (4 papers, 2017 to 2020). A benign or malignant brain and spinal cord tumor that arises from glial cells (astrocytes, oligodendrocytes, ependymal cells). "Because of the in-depth study in other field, such as glioma, much attention here has been put into the ASIC1a and ASIC3, and actually, these two isotypes indeed play great roles in the IVDD mechanism." (PMID 31526163, 2019). "Our data clearly show that glioma cells express functional ASIC1a and ASIC3, with substantial impact on patient survival." (PMID 29057936, 2017).
osteoarthritis (4 papers, 2012 to 2022). A noninflammatory degenerative joint disease occurring chiefly in older persons, characterized by degeneration of the articular cartilage, hypertrophy of bone at the margins and changes in the synovial membrane. "The ASIC3 inhibitor attenuated mechanical hyperalgesia by inhibiting the expression of ASIC3 in knee joint afferents and ASIC3 KO mice reversed mechanical hyperalgesia in a rat osteoarthritis model, which indicates the involvement of ASICs in osteoarthritis pain via the central nervous system." (PMID 33775217, 2021). "The purpose of this study was to clarify the role of ASIC3 in a rat model of osteoarthritis (OA) which is considered a degenerative rather than an inflammatory disease." (PMID 22909215, 2012).
angina (3 papers, 2005 to 2014). "In the heart, ASIC3 channels sense modest pH changes that occur during angina." (PMID 20844750, 2010). "For example, ASIC3 channels are activated by the modest changes in extracellular calcium and pH that accompany cardiac ischaemia and are highly expressed in a subset of cardiac sensory afferents that are presumed to transmit the pain of angina." (PMID 16242047, 2005).
hearing loss (3 papers, 2009 to 2021). "Inadequate response to pups' calls as a result of ASIC3-dependent hearing loss confers maternal deficits in caregivers and social development deficits in their young." (PMID 19652708, 2009). "With regard to the function of ASIC3 in hearing, ASIC3−/- mice have normal hearing at birth, but go on to develop hearing loss (4 months post birth); however, the mechanism for this early-onset hearing loss and any potential role of ASIC3 is not fully understood." (PMID 33258401, 2021).
rheumatic diseases (3 papers, 2022 to 2026). "LPC 16:0 has emerged as a key mediator of chronic joint pain in rheumatic diseases, acting through acid-sensing ion channel 3 (ASIC3)." (PMID 40001553, 2025). "This suggests a role for ASIC3 in triggering chronic joint pain, with potential implications of its inhibition for pain management in OA and possibly across other rheumatic diseases." (PMID 36287977, 2022).
breast carcinoma (2 papers, 2017). "We also confirmed the expression of ASIC3 and ASIC4 acid-sensing channels, as well as GPRs in all the mesenchymal cells analyzed, MSCs and osteoblasts, and CAFs that were directly isolated from BM of breast carcinoma." (PMID 28903357, 2017).
channelopathy (2 papers, 2023 to 2024). Channelopathies are a group of diseases caused by the dysfunction of ion channel subunits or their interacting proteins. "Indeed, ASIC3 contributes to proprioceptive mechanotransduction in a secondary manner, especially in the case of the theorized chronic Piezo2 channelopathy." (PMID 38534336, 2024). "Furthermore, acid-sensing ion channel 3 (ASIC3) is also known to activate WDR neurons in the spinal dorsal horn, and ASIC3 activation in intrafusal type II fibers is proposed in relation to type Ia proprioceptive terminal Piezo2 channelopathy in DOMS." (PMID 36983813, 2023). "Consequently, the suggested Piezo2 channelopathy may lead to excessive proton leak, glutamate excitotoxicity, acidosis, and intrafusal Type II afferent sensitization through ASIC3." (PMID 38534336, 2024).
Crohn disease (2 papers, 2015 to 2021). A gastrointestinal disorder characterized by chronic inflammation involving all layers of the intestinal wall, noncaseating granulomas affecting the intestinal wall and regional lymph nodes, and transmural fibrosis. "A possible role for ASIC3 in Crohn’s disease patients is demonstrated by biopsy samples showing a 2.5-fold increased expression of ASIC3, which was hypothesized to contribute toward visceral hypersensitivity in chronic inflammatory pain." (PMID 33258401, 2021). "Similar evidence was presented for acid sensing ion channels type 3 (ASIC3), as these were upregulated during active Crohn’s disease and contributed to peripheral sensitization by inflammatory mediators but were not involved in non-inflammatory visceral hypersensitivity according to another group." (PMID 25885345, 2015).
diabetes (2 papers, 2021 to 2024). "Beyond pain modulation, whether the proprioceptive DRG function regulated by ASIC3 is affected in diabetes needs further investigation." (PMID 37489658, 2024). "Research has shown that osthole can alleviate diabetic neuropathic pain through the P2X4 receptor and suppress the expression of acid-sensing ion channel 3 (ASIC3) in rat DRG to alleviate nucleus pulposus-evoked nociceptive responses." (PMID 34691215, 2021).
gastritis (2 papers, 2017 to 2019). Inflammation of the stomach. "In the upper gastrointestinal tract, ASIC3 has been suggested to play a major role in the development of inflammatory hypersensitivity to gastric acid, occurring during gastritis and peptic ulcer disease, both associated with painful symptoms." (PMID 31370176, 2019). "Disruption of the ASIC3 gene abolished the effect of gastritis and enhanced gastric acid-evoked expression of c-Fos in the brainstem." (PMID 29056828, 2017). "ASIC3 plays a major role in inflammatory hyperresponsiveness to gastric acid as it may occur in gastritis and peptic ulcer disease." (PMID 29056828, 2017). "In rats, intraperitoneal injection of APETx2 before experimentally inducing acute gastric mucosal lesions reduced gastric acidity, mucosal injury, and ASIC3 expression in thoracic DRG projecting to the stomach, suggesting a role for ASIC3 in the development of gastritis symptoms." (PMID 31370176, 2019).
Granuloma (2 papers, 2009 to 2021). A compact, organized collection of mature mononuclear phagocytes, which may be but is not necessarily accompanied by accessory features such as necrosis. "We provide a novel finding that ASIC3 participates in the maintenance of sub-acute-phase primary hyperalgesia in subcutaneous inflammation and mediates the process of granuloma formation and vasculitis in intramuscular inflammation." (PMID 19126241, 2009). "In inflamed muscle, ASIC3-/- mice seemed to display milder pathological features, including infiltration of leukocytes, formation of granulomas and vasculitis, than ASIC3+/+ mice." (PMID 19126241, 2009). "The mean density of granulomas was 0.80 ± 0.23/mm2 for ASIC3+/+ mice and 0.24 ± 0.08/mm2 for ASIC3-/- mice (p < 0.05)." (PMID 19126241, 2009). "ASIC3 could thus participate in the pathogenesis of granuloma formation and vasculitis through activating neurogenic inflammation." (PMID 19126241, 2009). "However, ASIC3-/- mice showed attenuated pathological features such as less CFA-induced granulomas and milder carrageenan-evoked vasculitis as compared with ASIC3+/+ mice." (PMID 19126241, 2009). "Well-formed granulomas defined by compact, well-circumscribed structures composed of epitheloid macrophages were characteristic of ASIC3+/+ mice, but most of the granulomas found in ASIC3-/- mice were small and ill-defined." (PMID 19126241, 2009). "ASIC3 participates in the development of sub-acute-phase hyperalgesia by up-regulating Nav1.9 and TTX-R currents in subcutaneous inflammation and mediates the process of granuloma formation or vasculitis in muscular inflammation." (PMID 19126241, 2009).
heart failure (2 papers, 2013 to 2026). Inability of the heart to pump blood at an adequate rate to meet tissue metabolic requirements. "ASIC3 may be further investigated as a potential therapeutic target in heart failure." (PMID 41808523, 2026). "Further study may explore whether or not activating ASIC3 could rescue the dysfunction of low-threshold baroreceptors that occurs in heart failure." (PMID 23490035, 2013).
Insulin resistance (2 papers, 2019 to 2021). Increased resistance towards insulin, that is, diminished effectiveness of insulin in reducing blood glucose levels. "However, in an analysis of 606 Taiwanese individuals, 33 possessed the ASIC3 rs2288646A polymorphism and this was associated with a statistically significantly lower frequency of insulin resistance and lower fasting serum insulin levels." (PMID 33258401, 2021).
keloid (2 papers, 2022 to 2023). An irregularly shaped, elevated mark on the skin caused by deposits of excessive amounts of collagen during wound healing. "ASIC3 mRNA expression was significantly increased in hypertrophic keloids and keloid-derived fibroblasts compared with expression in normal fibroblasts, and increased ASIC3 protein expression was confirmed by immunofluorescence staining analysis." (PMID 35661105, 2022). "We also found that ASIC3 expression was positively correlated with hypertrophic keloids and collagen expression in keloids." (PMID 35661105, 2022).
lumbar disc herniation (2 papers, 2015 to 2021). "Osthole was also found to reduce acid-sensing ion channel 3 (ASIC3) expression in rat dorsal root ganglion, which may contribute to its relieving chronic pain from lumbar disc herniation." (PMID 26246843, 2015).